LEF1 (lymphoid enhancer binding factor 1)
Diseases named in the same sentence as LEF1 in open-access papers (continued):
Sharing a sentence is not in itself a finding about the gene and the disease.
melanoma (continued). "Keeping in mind that phenotype switching in melanoma cells entails the exclusive expression of β-catenin cofactors LEF1 or TCF7L2, we interrogated whether SPARC can be integrated into this process, either in the presence or absence of PRRX1 expression." (PMID 40943659, 2025). "LEF1 mRNA was significantly reduced when we knocked down PANX1 in A375-P melanoma cells." (PMID 33647315, 2021). "Additionally, LEF1 has been reported as a Wnt/β-catenin target gene in several cell lines, including melanoma." (PMID 33647315, 2021). "Here, our results show that cinobufagin has an anti-cancer effect by inhibiting LEF1-mediated activation of Wnt/β-catenin signaling, especially in LEF1 high expressing melanoma cells, indicating that cinobufagin is a promising natural pharmaceutical agent for melanoma treatment." (PMID 32933177, 2020). "In addition, ectopic LEF1 expression is sufficient to attenuate cinobufagin-induced apoptosis and cell growth retardation in melanoma cells." (PMID 32933177, 2020). "Thus, we suggest that cinobufagin is a potential anti-melanoma drug that suppresses tumor-promoting Wnt/β-catenin signaling via LEF1 inhibition." (PMID 32933177, 2020). "Although previous studies indicate that Wnt/β-catenin signaling with LEF1, TCF4, and β-catenin expression is closely associated with melanoma growth and progression, it is still unclear whether LEF1 acts as a proliferative factor in melanoma." (PMID 32933177, 2020). "In addition, we found that LEF1, an essential transcriptional component of Wnt/β-catenin signaling, is aberrantly expressed in melanoma cells and involved in cell growth." (PMID 32933177, 2020). "LEF1 has been reported to enhance the invasive and proliferative of melanoma cells." (PMID 33289586, 2020). "To study whether LEF1 is required to suppress the expression of Wnt/β-catenin target genes, we analyzed c-Myc, Cyclin D1, and Axin-2 mRNA levels in LEF1 knocked-down A375 melanoma cells." (PMID 32933177, 2020). "Interestingly, the suppressive effect of cinobufagin on LEF1 and Wnt/β-catenin downstream target gene expression was diminished by LEF1 knock-down in A375 melanoma cells, suggesting that LEF1 is a potential molecular target of cinobufagin." (PMID 32933177, 2020). "To elucidate the regulatory mechanism by which suppression of TOP-flash reporter activity by cinobufagin treatment, we examined whether cinobufagin suppresses the expression of LEF1—a transcription factor activating Wnt/β-catenin signaling in melanoma cells." (PMID 32933177, 2020). "Initially, nuclear LEF1 levels in nine lung cancer cells and three melanoma cells were analyzed." (PMID 32933177, 2020). "Thus, AKT3, HDAC9, TCF12, and LEF1 were differentially expressed in the melanoma specimens, tracking with CD271 enrichment." (PMID 31118427, 2019). "In addition, there are multiple targets of MYC, LEF1, and E2F1 that are also associated with poor outcomes for melanoma patients." (PMID 29666373, 2018). "Both TCF4 and LEF1 are Wnt target genes but differential expression changes have been demonstrated in other models: as an example, in melanoma studies, LEF1 is prominent in differentiated/proliferative cells whilst dedifferentiated/invasive cells express TCF446." (PMID 29531810, 2018). "LEF1 has been shown to be highly expressed in proliferative cells in melanoma." (PMID 26405815, 2015). "In contrast, overexpression of mutated LEF1, lacking the DNA binding domain, results in reduced melanoma cell motility." (PMID 23224985, 2013). "Since the in silico analysis indicated the presence of LEF/TCF (T cell factor/Lymphoid Enhancer factor)-binding sites “A/T A/T CAAAG” within the SPARC proximal promoter, we explored whether endogenous LEF1 or TCF7L2 TFs could bind to this promoter region in melanoma cells." (PMID 40943659, 2025). "Thus, we attempted to determine whether LEF1 acts as a pro-survival factor for melanoma cell growth." (PMID 32933177, 2020).
melanoma (continued). "Interestingly, we found that cinobufagin decreased nuclear LEF1 levels in a dose-dependent manner in A375, G361, and A2058 melanoma cells, indicating that cinobufagin may attenuate canonical Wnt/β-catenin signaling by decreasing LEF1 expression in melanoma." (PMID 32933177, 2020). "Thus, it is conceivable that the preferential expression of LEF1 or TCFs could direct β-catenin activity to different subsets of WNT target genes in melanoma cells." (PMID 27175588, 2016). "Five hub genes including CXCL11, ICAM1, LEF1, MITF, and STAT1 were identified, SUZ12, SOX2, TCF3, NANOG, and SMAD4 were determined as the most significant TFs in metastatic-melanoma." (PMID 39820173, 2025). "LEF1 is preferentially expressed by differentiated and proliferative cells, whereas TCF7L2 is mostly expressed by undifferentiated and invasive melanoma cells, and is inversely correlated with the expression of LEF1." (PMID 40943659, 2025). "RPS14 overexpression promoted the development of colorectal carcinoma, and RPS14, a downstream target of zinc finger protein 280 A (ZNF280A), was upregulated in melanoma cells and has a co-binding site for YAP and β-catenin via LEF1/TEAD." (PMID 38388496, 2024). "Consistent with previous studies, we found that activated Wnt/β-catenin signaling, which involves LEF1, TCF4, and β-catenin is highly increased in melanoma." (PMID 32933177, 2020). "Abnormally increased levels of nuclear LEF1, TCF4, and β-catenin, which are essential transcriptional components of Wnt/β-catenin signaling, were observed in A375, A2058, and G361 melanoma cells." (PMID 32933177, 2020). "The interaction between beta-catenin, lymphoid enhancer-binding factor 1 (LEF1), and transcription factor 4 (TCF4) was studied in order to see its effects on melanoma." (PMID 31934531, 2019). "In melanoma cells, ICAT competes with LEF1 to negatively regulate the M-MITF and NEDD9 target genes." (PMID 28273108, 2017). "Up-regulation of β-Catenin-LEF1 and concomitant down-regulation of YAP1 have been found to sensitize MAPKi-resistant melanoma." (PMID 29285312, 2017). "It significantly reduced the transcript levels of LEF1, WNT10B, MITF-M, c-MYC and CCND1 and increased the mRNA levels of FZD7 and DKK1 in all melanoma cell populations." (PMID 27351373, 2016). "LEF1 and TCF7L2 are both co-factors of β-catenin and are phenotype-specific in melanoma." (PMID 40943659, 2025). "To this end, we first performed chromatin immunoprecipitation and found that TCF7L2 was significantly enriched in the SPARC promoter region (−175 to −25 nt relative to the TIS) in several melanoma cell lines tested, whereas LEF1 was not." (PMID 40943659, 2025). "As we clearly revealed no β-catenin/LEF1/TCF activity in several melanoma cell lines, a literature search suggested that β-catenin also acts as a co-factor for YAP signaling." (PMID 38388496, 2024). "Finally, to further assess the functional contribution of Wnt/β-catenin transcriptional output to melanoma cell phenotype switching we ablated the expression of TCF4 and LEF1, the TCF family members predominantly expressed in melanoma cells." (PMID 34819356, 2022). "LEF1 suppression attenuated cell viability in LEF1-high expressing melanoma cells but not LEF1-low expressing A549, H358, and Calu-1 lung cancer cells." (PMID 32933177, 2020). "In this study, we found that LEF1 is highly expressed in A375, A2058, and G361 melanoma but not various lung cancer cells." (PMID 32933177, 2020). "LEF1 suppression decreased viability in melanoma but not lung cancer cells, indicating that LEF1 acts as a pro-survival factor at least in LEF1-high expressing melanoma cells." (PMID 32933177, 2020). "Although several reports have shown that LEF1 is highly expressed in melanoma, the functional role of LEF1 in melanoma growth is not fully understood." (PMID 32933177, 2020).
melanoma (continued). "Indeed, aberrant Wnt/β-catenin signaling pathway expression, which increases nuclear β-catenin, LEF1, and TCF4 levels, has been observed in various cancers, including melanoma." (PMID 32933177, 2020). "Our study revealed that LEF1 suppression induced cell growth retardation and apoptosis in LEF1-high expressing melanoma cells but not in LEF1-low expressing A549 lung cancer cells." (PMID 32933177, 2020). "Additionally, it has been reported that the differential expression of LEF1 and TCF4 determines the proliferative and invasive potentials of melanoma subtypes." (PMID 32933177, 2020). "Studies in melanocytes indicate that β-catenin and LEF1 synergistically regulate expression from the MITF-M promoter through the LEF1 binding sites and overexpression of β-catenin induces the expression of MITF in melanoma." (PMID 27428965, 2016). "Indeed, LEF1 and ROR1 are expressed by a variety of human cancers including melanoma, colorectal cancer, pancreatic cancer and lung cancer." (PMID 26050196, 2015). "No data are available on the TCF/LEF1-TEAD interaction in melanoma." (PMID 38388496, 2024). "MITF-M, in cooperation with Lef1, also regulates its own gene transcription in M14 cells, and this, in turn, could result in differential regulation of gene expression downstream of MITF-M that we observe in the TXNRD1+/− melanoma cells." (PMID 36291795, 2022). "Our data underscore the fact that LEF-1 and IL-21R are requisite for the persistence of Cbx3/HP1γ-deficient CD8+ effector T cells in tumors with varied mutation loads that are ICB responsive (B16 melanoma) or non-responsive (ovarian and NBL)." (PMID 34721405, 2021). "In addition, decreased β-catenin but not TCF4 levels were observed in LEF1 knocked-down melanoma cells." (PMID 32933177, 2020). "Predominant expression levels of LEF1 and β-catenin, but not TCF4, have been observed in highly metastatic melanoma cells such as MM-AN, MM-BP, RPM-EP, and MM-RU cells." (PMID 32933177, 2020). "In this study, ICAT overexpression in melanoma cells was found to negatively regulate M-MITF and NEDD9 promoter activities, both in the presence and absence of ectopic LEF1." (PMID 28273108, 2017). "However, LEF1 is presumably not the only mediator of FN1 expression, as FN1 is also expressed in cells lacking LEF1, for instance melanoma-derived MV3 cells." (PMID 23677615, 2013).
colorectal cancer (43 papers, 2009 to 2025). A primary or metastatic malignant neoplasm that affects the colon or rectum. "The results of the correlation analysis indicated a positive association between the expression levels of β-catenin and LEF1 in colorectal cancer." (PMID 37657935, 2023). "Further, enriched transcription factor LEF1 is implicated in tumorigenesis and cancer cell proliferation, migration, invasion, and stemness in multiple cancer (e.g., colorectal cancer, AML, oral squamous cell carcinoma)." (PMID 31068808, 2019). "In Kaplan-Meier analyses LEF-1 positivity associated with a significant better 5- and 10 year survival of patients with colorectal cancer than LEF-1 negativity (p = 0.015)." (PMID 21092222, 2010). "Also, the presence of increased LEF1 is associated with an increased risk for primary colorectal cancer and liver metastasis." (PMID 38003292, 2023). "In colorectal cancer, LEF1 is well known to have critical role in cancer stem-like cell survival and self-renewal, and disruption of the LEF1 pathway can be reduce recurrence." (PMID 38338902, 2024). "In colorectal cancer, β‐catenin interacts with lymphoid enhancing factor (LEF‐1) and Krüppel‐like factor 4 (KLF4) to increase or decrease tumor cell proliferation, respectively." (PMID 38826147, 2024). "By targeting lymphoid enhancer-binding factor 1, miR-493-3p reduced colorectal cancer EMT and metastasis." (PMID 36762306, 2023). "Here, we demonstrate that LEF1 undergoes condensation into droplets with β-catenin upon Wnt signaling activation in colorectal cancer cells." (PMID 37657935, 2023). "This research elucidates the correlation between liquid–liquid phase separation (LLPS) of LEF1 with β-catenin and their transcriptional activation function, offering a novel therapeutic approach for the treatment of colorectal cancer through LLPS." (PMID 37657935, 2023). "Overexpression of miR-449a significantly suppress the progression of colorectal cancer by affecting the expression of target genes LEF-1 and cyclin D1." (PMID 36545680, 2022). "Recent research suggests that LEF1 can promote cell growth and inhibit cell apoptosis in such cancers as colorectal cancer, lung cancer, and hepatocellular carcinoma (20, –, 22)." (PMID 34096776, 2021). "EphrinB2 (EPHB2) expression in a mouse model of colorectal cancer is subject to competing positive regulation by Tcf7l2 and negative regulation by Lef1." (PMID 32403323, 2020). "The expression of miR-219-5p was shown to be decreased in colorectal cancer and to inhibit colorectal cancer metastasis and epithelial-mesenchymal transition by targeting LEF1 to inactivate the AKT and ERK pathways." (PMID 31753039, 2019). "To investigate the effect of hypoxia on Wnt/β-catenin signaling in colorectal-cancer cells, we thus examined the quantitative changes in the expression of positive (Wnt1, Lef1, cyclin D1) regulators of Wnt/β-catenin signaling with or without hypoxia." (PMID 26965643, 2016). "The findings from this study revealed an inherent role of 5-HT1DR which binds Axin1 and dissociates β-catenin from the complex, moving β-catenin into the nucleus to activate the β-catenin/LEF1/TCF4/MMP-7 pathway in colorectal cancer metastasis." (PMID 26214021, 2015). "Further down the list, Foxa2 (1.32, rank 10/284) is known to regulate lipid metabolism and ketogenesis related genes in liver, and Lef1 (1.31, rank 11/284) is a prognostic biomarker for liver metastasis in colorectal cancer." (PMID 24238150, 2013). "Our findings were consistent with those from colorectal cancers, in the sense that Lef1 expression was higher in cohorts with good prognosis." (PMID 22792274, 2012). "Beta-catenin, as a transcription factor complexed with TCF4, is known to upregulate expression of many relevant proteins in colorectal cancer, such as c-myc, cyclin D1, LEF-1, CD44, and c-jun." (PMID 22682314, 2012).
colorectal cancer (continued). "In colorectal cancer, Lef1 expression is a prognostic factor related to survival, with high levels of Lef1 correlating with longer survival times." (PMID 22792274, 2012). "LEF-1 expression has been previously utilised as a marker in different tumour entities like acute lymphoblastic leukaemia, oral squamous cell carcinoma, and colorectal cancer to identify Wnt/β-catenin activated tumours." (PMID 40130164, 2025). "Importantly, LEF1’s promotion of proliferation and migration in colorectal cancer cells is contingent upon its IDR-dependent LLPS." (PMID 39757214, 2025). "LEF1 activation is known to induce EMT in colorectal carcinoma cells." (PMID 40141294, 2025). "Additionally, a study by Wang found an association between increased LEF1 expression and LNM, distant metastasis, advanced TNM staging, and poorer prognosis in colorectal cancer." (PMID 38181281, 2024). "Thus, the nuclear expressions of LEF1 and β-catenin increased at the invasive front of colorectal cancer, thereby showcasing their correlation with the upregulation of Wnt target genes, cell mobility, and tumor invasion." (PMID 38181281, 2024). "Subsequently, we analyzed the correlation between β-catenin and LEF1 in colorectal cancer." (PMID 37657935, 2023). "Importantly, LEF1 promotes the proliferation and migration of colorectal cancer cells in an IDR-dependent manner." (PMID 37657935, 2023). "Furthermore, a growing body of evidence suggested that LEF1 acted as an oncogene in various forms of malignant tumors, including colorectal cancer, lung cancer, and hepatocellular carcinoma (20, –, 22)." (PMID 34096776, 2021). "Furthermore, decreased cellular motility and invasiveness have been observed in LEF1 knocked-down colorectal cancer cells." (PMID 32933177, 2020). "There is clear correlation of transcripts indicative of regulation of cell migration with LEF1 in tumor tissue, consistent with the previously suggested prognostic value of increased LEF1 expression in colorectal cancer for both increased metastasis and for shorter survival prospects of patients." (PMID 32403323, 2020). "In our study LEF-1 expression in colorectal cancer correlated with an improved patient survival." (PMID 21092222, 2010). "The DNA binding proteins and transcription factors TCF4 and LEF-1 are partners of nuclear β-catenin and effectors of the Wnt/β-catenin signalling pathway, which is decisively involved in tumorigenesis and progression of colorectal cancer." (PMID 21092222, 2010). "These surprising findings suggest that TCF4 might be the main binding partner for β-catenin during development and progression of colorectal cancer whereas an enhancement of Wnt/β-catenin transcriptional activity by a switch from TCF4 to LEF-1 is unlikely." (PMID 21092222, 2010). "Finally, LEF1 is an essential factor for stem cell maintenance and organ development, as its inhibition by Niclosamide attenuates cancer stemness and therapy resistance in colorectal cancer." (PMID 36566021, 2022). "We found that rs11954856 in the APC gene was associated with colorectal cancer and could increase the expression levels of APC, β-catenin, TCF7L1, TCF7L2 and LEF1 genes in the pathway in the CRC patients, demonstrating the involvement of APC in the pathological processes leading to CRC." (PMID 29050326, 2017). "Thus further understanding of the mechanism by which Rac1 modulates the interaction between LEF-1 and β-catenin may provide an alternative therapeutic avenue to reduce β-catenin–LEF-1 signaling in colorectal cancer." (PMID 26403202, 2015). "In colorectal cancer patients, the overexpression of LEF1 represented a risk factor for the poor overall survival of CRC patients, and increased expression of LEF1 with decreased expression of Notch2 could be used to facilitate the early detection of colorectal cancer." (PMID 31296250, 2019). "Immunohistochemical analyses of LEF-1, TCF4 and nuclear β-Catenin were done using a tissue microarray with 214 colorectal cancer specimens." (PMID 21092222, 2010).